CXCL10 (C-X-C motif chemokine ligand 10)
Diseases named in the same sentence as CXCL10 in open-access papers (continued):
Sharing a sentence is not in itself a finding about the gene and the disease.
ischemia (13 papers, 2014 to 2025). A hypoperfusion of the BLOOD through an organ or tissue caused by a PATHOLOGIC CONSTRICTION or obstruction of its BLOOD VESSELS, or an absence of BLOOD CIRCULATION. "In this study, we found that upregulation of CXCL10 is associated with increases in ER stress-related genes in ischemia-injured retina and blocking ER stress attenuates CXCL10 expression." (PMID 26448323, 2015). "Both CXCR3 and CXCL10 deficiencies resulted in decreased perfusion recovery in a murine hindlimb ischemia model." (PMID 24868552, 2014). "Multiple microglia-related genes such as Cxcl10, Tlr7, Cd86, Tnfrsf1a, Nfkbia, Tgfb1, Ccl2 and Il-6, were upregulated with prolonged ischemia." (PMID 35154109, 2022). "Remarkably, ischemia-associated microglia (amoeboid-like CXCL10+ cells lacking P2RY12 and TMEM119 protein expression) filled the lesion core." (PMID 32573436, 2020). "Additionally, CXCL10 has been recognized to be a marker of oxidative stress and inflammation, and its inhibition in astrocytes and microglia/macrophages aids in the attenuation of oxidative stress‐induced inflammation following ischemia‐reperfusion injury." (PMID 34459123, 2021). "In CXCL10−/− and TLR4−/− mice of hepatic ischemia/reperfusion injury plus major hepatectomy (IRH) model, monocytic MDSCs, instead of granulocytic MDSCs, were significantly decreased." (PMID 33990548, 2021). "In conclusion, these results indicate that ER stress-medicated activation of CXCL10/CXCR3 pathway has an important role in retinal inflammation and neuronal injury after high IOP-induced ischemia." (PMID 26448323, 2015). "Notably, the degrees of CXC motif chemokine 10 (CXCL10) and interleukin-6 (IL-6) were >20, suggesting they may have an important role in MCAO-induced ischemia." (PMID 25333814, 2015).
lung adenocarcinoma (13 papers, 2018 to 2025). A carcinoma that arises from the lung and is characterized by the presence of malignant glandular epithelial cells. "By using the UALCAN and GEPIA2 databases, we observed that ACE2 and CXCL10 are mostly overexpressed in lung adenocarcinoma (LUAD) and lung squamous cell carcinoma (LUSC)." (PMID 33585826, 2021). "This is consistent with a recent study showing that CD8 expression in lung adenocarcinoma is positively correlated with CCL5 and CXCL10 expression." (PMID 38062129, 2024). "Analysis of NSCLC data from The Cancer Genome Atlas (TCGA) identified a strong correlation (Spearman correlation coefficient >0.55) among the expression of CXCL9, CXCL10, and their cognate receptor (CXCR3) in both lung adenocarcinoma (LUAD) and lung squamous carcinoma (LUSC)." (PMID 38518770, 2024).
myositis (13 papers, 2014 to 2025). "Similar elevations of cytokines associated with type 1 inflammation, including CXCL9, CXCL10, IFN-γ, IL-12, and TNF have been demonstrated at the protein level in serum of IBM patients versus non-myositis controls." (PMID 40034760, 2025). "Previous studies have also shown elevated muscle levels of numerous cytokines associated with type 1 inflammation, including CCL5, CXCL9, CXCL10, CXCL11, IFNG, and TNF in IBM patients compared to various myositis and non-myositis controls." (PMID 40034760, 2025). "In myositis patients, serum CXCL10 levels were significantly increased 9.6-fold compared to healthy controls and 4.2-fold compared to disease controls." (PMID 37891738, 2023). "We propose adding circulating CXCL10 and GDF15 to the blood-based diagnostic toolkit for myositis as a valuable patient-friendly approach." (PMID 37891738, 2023). "A threshold of 180 pg/mL of CXCL10 differentiates myositis patients from healthy and disease controls with a sensitivity of 0.80 and a specificity of 0.71." (PMID 37891738, 2023). "The results of this study revealed the CXCL10 as an important chemoattractant for monocytes, dendritic cells, and T-cells, which are present in the biopsy specimens of myositis patients and in their plasma also." (PMID 32775472, 2020). "With the threshold set to 180 pg/mL of CXCL10, myositis patients could be differentiated from healthy and disease controls with a sensitivity of 0.80 and a specificity of 0.71." (PMID 37891738, 2023). "Other studies have suggested also the CXCL10 to be a therapeutic target in adult myositis patients." (PMID 32775472, 2020). "So far, we speculate that pharmacological targeting systemic and especially local muscular CXCL10 production with VDR agonists could result a particularly advantageous approach from the early stage of myositis." (PMID 24895631, 2014). "Importantly, we showed that CXCL10 levels aid in differentiating IIMs from hereditary muscle disorders, with the latter often displaying secondary inflammatory changes that can be confused with myositis." (PMID 37891738, 2023). "CXCL10 blockade with monoclonal antibody suppresses inflammation in muscle, which suggests CXCL10 inhibition could be used as a potential therapeutic strategy for treatment of myositis." (PMID 24939012, 2014). "Of interest, CXCR3 ligands, CXCL9 and CXCL10, are increased in the serum of Jo1+ and SRP+ myositis patients, and CXCL10 is a validated disease activity biomarker for juvenile dermatomyositis." (PMID 35371068, 2022). "An in vitro study on primary human muscle cell cultures from myositis patients showed that immunoproteasome is involved in the maintenance of myokines (IL-6, IL-1β, CXCL9, and CXCL10) production and in MHC I overexpression." (PMID 32775472, 2020). "Our study found significant elevation of serum CXCL10 and GDF15 levels in myositis patients." (PMID 37891738, 2023). "First, the expression of CXCL10 and CXCR3 in C-protein induced myositis mice was investigated." (PMID 24939012, 2014). "In particular, chemokines, a class of small cytokines with potent chemotactic activity, such as IL-8 (CXCL8), Mig (CXCL9), IP-10 (CXCL10), RANTES (CCL5), and MCP-1 (CCL2), are overexpressed during myositis in infiltrating inflammatory cells, extracellular matrix, and muscle fibers." (PMID 24895631, 2014). "We propose that circulating CXCL10 and GDF15 levels could be of aid to diagnose myositis." (PMID 37891738, 2023).
respiratory infections (13 papers, 2012 to 2025). "Another hallmark of a respiratory infection observed both in animal models and human studies is the expression of CXCL10 at both the transcriptome and the proteome level." (PMID 41346583, 2025). "The inflammatory chemokine interferon-gamma inducible protein (IP-10), also known as C-X-C motif chemokine ligand 10 (CXCL10), is a biomarker associated with several inflammatory disorders and associated with respiratory infections." (PMID 36996064, 2023). "In humans, little is known about CXCL10/CXCR3 in the context of respiratory infections." (PMID 31815739, 2020). "Hence, controlling for respiratory infections or excluding children with wheezy bronchitis did not essentially affect the associations of IL-5, IL-13, CXCL10, IgA, and TGF-β1 in both serum and whey with AS." (PMID 22805009, 2012).
steatosis (13 papers, 2020 to 2025). Increased lipid within the cytoplasm of cells. "Consistent with the observation that inhibiting CXCL10 suppresses the development of steatohepatitis in mice, the results reveal that CXCL10 is implicated in steatosis via up-regulation of SREBP1c and liver X-activated receptor (LXR)." (PMID 37020540, 2023). "The release of CXCL10 from macrophages is induced by steatosis and deficiency of macrophage lipid receptor CD36 led to reduced release of CXCL10 in the liver." (PMID 36276076, 2022). "In addition, some experimental data indicated that CXCL10 promoted steatosis by activating macrophages, hence causing associated fibrosis and hepatic injury in NASH." (PMID 33042108, 2020). "MiR-223 is crucial in controlling the progression from steatosis to MASH by inhibiting Cxcl10 and Taz expression in the liver." (PMID 40668532, 2025). "Additional pro-inflammatory cytokines have also been explored as steatohepatitis biomarkers, demonstrating moderate accuracy for discriminating between steatohepatitis and simple steatosis (e.g., CXCL10 with an AUROC of 0.68)." (PMID 38809396, 2024). "Derived from macrophage p38α-deficient mice, the primary hepatocytes showed decreased steatosis and inflammatory damage through reduced secretion of pro-inflammatory cytokines (TNF-α, CXCL10, and IL-6), which regulate M1 macrophage polarization." (PMID 36984693, 2023). "MiR-223 plays a key role in controlling steatosis-to-NASH progression by inhibiting expression of Cxcl10 and transcriptional co-activator with PDZ-binding motif (Taz) in the liver." (PMID 35371024, 2022). "CXCL10 (r = 0.55, P = 2.37 × 10–4) was the most relevant gene with the steatosis grade, and THY1 (r = 0.67, P = 2.04 × 10–6) was the most relevant gene with the fibrosis stage." (PMID 34419146, 2021). "The result was similar to another M3 correlated gene CXCL10, which was also relevant to the steatosis grade." (PMID 34419146, 2021). "Additionally, the results of AH patients, NIAAA, and ALD mouse models have indicated that excessive alcohol consumption inhibits the ADRB2/SIRT1/PGC-1α/PPARα pathway, leading to elevated levels of oxidative stress and cytokines such as CCL2, CXCL8, and CXCL10, accompanied by hepatic steatosis." (PMID 39640486, 2024). "CXCL10 expression is increased in MASH patients, and the depletion of CXCL10 in murine MASH models has been documented to decrease steatosis, liver injury, and fibrosis." (PMID 38892602, 2024). "We found that CXCL10 upregulated in NAFL and NASH samples, and was indeed the most relevant gene with the steatosis grade." (PMID 34419146, 2021). "The latest research proved that miR-223 plays a key role in controlling steatosis-to-NASH progression by inhibiting two downstream targets, Cxcl10 and Taz." (PMID 33928027, 2021).
atopic dermatitis (12 papers, 2011 to 2025). "The results showed that CSSH reduced pro-inflammatory cytokines (IL-1β, IL-6, IL-8, MCP-1 and CXCL10) and atopic dermatitis-related cytokines (IL-4, CCL17, MDC and RANTES) in TNF-α/IFN-γ-induced HaCaT cells." (PMID 38931136, 2024). "Thus, we propose that neutrophils promote chronic itch in atopic dermatitis via upregulation of CXCL10 and subsequent activation of CXCR3-dependent itch pathways." (PMID 31631836, 2019). "In addition, the gene expression levels of IL-4, IL-13, CXCL10, CCL5, CCL17, and CCL22, which are related to atopic dermatitis, were significantly decreased by HCFE in DPM-stimulated HaCaT cells." (PMID 39599592, 2024). "In addition, the expression of IL-4, IL-13, CXCL10, CCL5, CCL17, and CCL22, which are atopic dermatitis mediators, increased 2- or 3-fold in HaCaT cells treated with DPM compared with that in the control group." (PMID 39599592, 2024).
liver cancer (12 papers, 2015 to 2025). An epithelial or non-epithelial malignant neoplasm that arises from the liver. "CXCL2 and CXCL10 are genes enriched by Chemokine signaling pathway; CXCL2 promotes the proliferation and metastasis of liver cancer cells; and CXCL10 is associated with enhanced T cell infiltration in tumors." (PMID 35463358, 2022). "More importantly, CXCL10 has been identified as a major biological marker mediating disease severity and may be used as a prognostic indicator for various diseases, thus, its possible role as disease severity biomarker for liver cancers should be further evaluated." (PMID 32256215, 2020). "While PD-L1 is not uniformly overexpressed across all tumors, CXCL10 consistently exhibits elevated levels in tumors, particularly in lung, colon, and liver cancers, as a reliable biomarker for predicting immunotherapeutic efficacy." (PMID 38953994, 2024). "Among those, CXCL5, CXCL9, CXCL10, and CXCL11 were significantly elevated in patients with early HCC according to the Barcelona Clinic Liver Cancer (BCLC) stages 0/A compared to cirrhotic controls without HCC." (PMID 36982370, 2023).
meningitis (12 papers, 2017 to 2025). A disorder characterized by acute inflammation of the meninges of the brain and/or spinal cord. "Ccl3 and Cxcl10 expression induction was by trend less severe in Ac2-26-treated meningitis mice (p > 0.05; two-way ANOVA followed by Bonferroni test)." (PMID 33121515, 2020). "In infected WT mice, Streptococcus pneumoniae-induced meningitis lead to a robust and significant increase of Ccl3 and Cxcl10 expression levels." (PMID 33121515, 2020). "High levels of CXCL9 and CXCL10 are detected in CSF of herpes simplex encephalitis and meningitis patients, whereas CXCL11 is exclusively found in herpes simplex meningitis patients." (PMID 30777092, 2019). "Newly-weaned hamsters had higher brain viral load, significantly increased cerebrospinal fluid concentration of TNF-α and CXCL10 and inflammatory damages including mild meningitis and parenchymal vascular congestion, despite sparse expression of nucleocapsid antigen in brain cells." (PMID 37122119, 2023). "have also found inflammatory markers elevated in the CSF during VZV-related meningitis, including interferon gamma, interleukins IL-6, IL-8, IL-10, IL-17F, IL-1RA, chemokines CXCL-9, CXCL-10, CCL-2 and G-CSF." (PMID 40416981, 2025).
renal fibrosis (12 papers, 2010 to 2024). A final common manifestation of a wide variety of chronic kidney diseases characterized by glomerulosclerosis and tubulointerstitial fibrosis. "For example, Cxcl10, which is upregulated in aged large artery, capillary, and angiogenic ECs, has been linked to progressive renal fibrosis and the recruitment of macrophages into the kidney." (PMID 37214419, 2023). "Cx43 mediates the release of ATP from TECs during renal injury, inducing peritubular macrophage pyroptosis, which subsequently leads to the release of CXCL10 and activation of intrarenal fibroblasts and acceleration of renal fibrosis." (PMID 35641484, 2022). "At the same time, expression of inflammatory cytokines (Il1b, Csf2, Tnfa, and Cxcl10), renal fibrosis, and profibrotic genes (Col1a1, Col3a1, Fn1, and Vim) was lower in the FA-treated Casp9 HZ mice." (PMID 34739325, 2021). "In animal models, inhibition of CXCL10/CXCR3 could result in progressive renal fibrosis by upregulating the expression of TGF-β." (PMID 35281025, 2022). "The canonical stimulation for renal fibrosis has been recognized as TGF-β1, TNF-α, MCP-1, and CXCL-10." (PMID 36203223, 2022). "On the contrary, recombinant murine CXCL10 reduces many indices of CKD in diabetic mice and blocking CXCL10 promotes progressive renal fibrosis." (PMID 35806457, 2022). "In addition, the elevated secretion of pro-inflammatory cytokines, including M1-related CXCL1 and CXCL10 and M2-related CCL17 and CCL26, may augment in the early phase of renal inflammation and in the late phase of renal fibrosis in folic acid-induced RIF." (PMID 35990680, 2022).
anemia (11 papers, 2013 to 2026). A reduction in the number of red blood cells, the amount of hemoglobin, and/or the volume of packed red blood cells. "On the other hand, the circulating levels of IL-1β, IL-8, CXCL10, IL-6, CCL4, IL-1RA and CCL2 displayed an inverse behavior, with rising levels being proportional to increases in anemia severity." (PMID 37143662, 2023). "IL-2, sIL-2R, IL-6, IL-8, IL-12, IL-17, MCP-1/CCL2, and MIP-1α correlate with anemia/RBC transfusion dependency while IL-6, IP-10/CXCL-10 and MIP-1β correlate with thrombocytopenia." (PMID 37760903, 2023). "The negative correlations between CXCL10 and IL-6 with Hb indicate potential links to anemia and hemolysis in SCD patients, suggesting that higher levels of these biomarkers are associated with worse hematological outcomes." (PMID 39749215, 2024). "On the other hand, higher IP-10/CXCL10 plasma levels, as well as IFN-γ and IL-10, were observed in vivax malaria patients with mild anaemia in comparison to no anaemia." (PMID 28118834, 2017).
dyslipidemia (11 papers, 2016 to 2025). "Additionally, the inverse associations of CXCR3+ T lymphocytes with dyslipidemia suggest their recruitment to adipose tissue by CXCL10 or CXCL11." (PMID 39109081, 2024). "Conversely, the upregulation of proteins such as HGF and CCL19, along with increased inflammatory cytokines like IL-6, CXCL10, and CCL8, suggests an inflammatory environment that could predispose OBO individuals to the development of a metabolic syndrome." (PMID 40076884, 2025). "Specifically, we demonstrate reduction of liver inflammation and subsequent liver injury and fibrosis in CXCL10-null mice, independent of effects on weight gain and parameters of the metabolic syndrome." (PMID 27349927, 2016). "In summary, we demonstrate a salutary effect of CXCL10 genetic deletion in a preclinical model of NASH pathogenesis independent of body weight and the metabolic syndrome." (PMID 27349927, 2016).
interstitial lung disease (11 papers, 2012 to 2026). A diverse group of lung diseases that affect the lung parenchyma. "A recent study sought to correlate CXCL10 levels in BAL supernatant with serum but in a heterogeneous cohort of 16 patients with collagen vascular diseases-interstitial lung disease (CVDs-ILD) of which 5 were patients with SSc-ILD." (PMID 37995465, 2023). "Patients with silicosis have increased circulating dsDNA and CXCL10 in sputum, and patients with fibrotic interstitial lung disease display STING activation and CXCL10 in the lung." (PMID 30523277, 2018).
Pleural effusion (11 papers, 2009 to 2022). The presence of an excessive amount of fluid in the pleural cavity. "CXCL10 is selectively up-regulated in TB pleural effusions compared with malignant effusions and in lateral flow based test it showed promise as a diagnostic tool for pleural TB." (PMID 29764370, 2018). "Notably, similar effects were observed when we stimulated fibroblasts with CM from patient-derived cancer cells that were collected from pleural effusions or ascites of metastatic breast cancer patients, inducing CXCL10 in fibroblasts in an NF-κB-dependent manner." (PMID 32198421, 2020).
Anxiety (10 papers, 2016 to 2025). Intense feelings of nervousness, tension, or panic often arise in response to interpersonal stresses. "The early onset TSD mouse model Hexa−/−Neu3−/− mice demonstrated a high level of anxiety, along with elevated levels of Ccl2, Ccl3, Ccl4, Cxcl10." (PMID 39905541, 2025). "In contrast to the placenta, the female fetal brain was unique in that CXCL10, a chemokine that has been identified as an inflammatory contributor to anxiety in mice, was selectively elevated at 2 h after MIA." (PMID 31611335, 2019). "We previously reported that LPS-induced anxiety-like behavior in adult male mice positively correlated with IL-6 and CCL2 levels in the plasma and chemokine (CXCL10 and CCL2) expression in the brain." (PMID 36698151, 2023).
astrocytoma (10 papers, 2015 to 2025). "CHIKV infection in astrocytoma cells produced a robust induction of CXCL10 and TNF-α, two inflammatory genes well documented for their role in enhancing the severity of disease in human cases as well as in mouse models of infection." (PMID 35746681, 2022). "Infection with RVFV induced significant upregulation of ATF3, FOS, KLF4, CXCL10, TNF-α, and PTGS2 in astrocytoma cells at 16 hpi." (PMID 35746681, 2022). "Astrocytoma cells incubated with TNFα and IFNγ and subsequently treated with setmelanotide exhibited reduced expression of chemokine C–C motif ligand 2 (CCL2) and C-X-C motif chemokine 10 (CXCL10), while IL-6 and IL-11 mRNA levels were increased." (PMID 37957462, 2023). "Infection of astrocytoma cells with SINV, another Old World alphavirus, significantly induced transcription of CXCL10 and TNF-α, but neither were dependent on EGR1." (PMID 35746681, 2022).